LINC02315 (long independently transcribed non-coding RNA 2315)
Gene: Long non-coding RNA gene on chromosome 14 (40,954,415 to 41,149,579, forward strand). Ensembl gene ENSG00000251363.
Diseases named in the same sentence as LINC02315 in open-access papers:
LINC02315 is named in the same sentence as 1 disease in open-access papers, as found by Europe PMC text mining. Sharing a sentence is not in itself a finding about the gene and the disease. The quoted sentences say what the papers report.
osteosarcoma (1 paper, 2021). A usually aggressive malignant bone-forming mesenchymal neoplasm, predominantly affecting adolescents and young adults. "Results of survival analysis showed that osteosarcoma with high expression of AC006033.2, LINC02315, AL133523.1, USP30-AS1, or AC079760.2 had a better prognosis." (PMID 34692688, 2021).